NOTCH1 (notch receptor 1)
Diseases named in the same sentence as NOTCH1 in open-access papers (continued):
Sharing a sentence is not in itself a finding about the gene and the disease.
colon carcinoma (continued). "In colon carcinoma cells, DDR1 regulates the cleavage of Notch 1 by a γ-secretase and the subsequent release and translocation of its intracellular domain to the nucleus to stimulate pro-survival genes." (PMID 32582700, 2020). "Recently, we and others have shown that NOTCH1 signaling is key to CRC progression and should be exploited clinically, especially in patients already diagnosed with high-grade polyps or localized colon cancer." (PMID 32630477, 2020). "Notch1 and its target gene, hairy-enhancer-of-split (HES1), are expressed more in advanced colon tumors than in low-grade tumors." (PMID 32630477, 2020). "By comparing the transcriptomic profile of colon cancer-cocultured MCs versus control MCs, we identified a number of deregulated genes, such as MMP-2, VEGF-A, PDGF-A, COX2, NOTCH1 and ISG15, which contribute to the enrichment of cancer-related pathways." (PMID 30987352, 2019). "NOTCH1 and DTX2 were important factors in NOTCH signaling pathway and therapeutic targets in colon cancer treatment." (PMID 31596728, 2019). "Therefore, we hypothesize that NOTCH1 acts as an oncogene in colon cancer." (PMID 28947978, 2017). "mRNA expression levels of NOTCH-1, NOTCH-3, NOTCH-4, JAG-1, DLL-4, Hes-1, and Hey-1 were quantified to elucidate the action of endostatin/CTX on the notch signaling pathway in colon cancer." (PMID 26762567, 2016). "Further, EMT and stemness genes were up-regulated in Notch1High sub-population, suggesting the clear involvement of Notch1 signaling in EMT and CSCs in breast and colon cancer cells." (PMID 26046801, 2015). "The expression between Numb and Notch-1 showed negative correlation in colon cancer tissues (r=−0.261, p<0.05)." (PMID 39691600, 2024). "In addition, some studies have found that the activation of Notch1/Hes1 signaling pathway, as a downstream pathway of SIRT1, can induce apoptosis in esophageal squamous cell carcinoma and colon cancer cells, as well as inhibit their lymph node metastasis." (PMID 38828455, 2024). "By detecting the expression of Notch-1 protein and Numb protein in colon cancer and MLN, this study provides a possible theoretical basis for the occurrence, development, and metastasis of colon cancer." (PMID 39691600, 2024). "Immunohistochemical method was used to detect the expression of Notch-1 protein and Numb protein in 110 cases of colon cancer tissues, along with tumor adjacent tissues and 56 cases of MLN tissues, and to analyze its role in colon cancer and MLN tissue." (PMID 39691600, 2024). "Similarly, pharmacological inhibition of Cbl-b results in increased Notch1, T-cell functions, anti-cancer response and resistance to immunosuppression in TNBC and colon cancer models." (PMID 36090975, 2022). "Therefore, we measured the tumor protein levels of Notch1 and TGF-β in this study when we found that the combination of LUT and CUR synergistically inhibited colon cancer both in cultured cells and xenograft mice." (PMID 35740666, 2022). "Similarly, the overexpression of miR-195-5p and miR-139-5p sensitized colon cancer cells to 5-FU through decreased expression of Notch2/RBP-jκ and Notch1, respectively." (PMID 34680255, 2021). "A significant overlap was detected with several relevant gene families, including colon cancer progression (e.g., FN1, IGBP3, PLAUR and TIMP1; P=0.00052), tumour cell apoptosis (e.g., BID, TNFRSF21, PHLDA1 and NOTCH1; P=1.46 × 10–6) and cell proliferation (e.g., CTGF, SPP1, FOLR1 and SPARC)." (PMID 21119668, 2010).
colon carcinoma (continued). "In colon cancer and triple-negative breast cancer, hypoxia upregulated ORAI1 by the Notch1 pathway." (PMID 38672434, 2024).
cervical carcinoma (71 papers, 2010 to 2026). A carcinoma arising from either the exocervical squamous epithelium or the endocervical glandular epithelium. "In cervical cancer, the loss of nuclear NOTCH1 was reported to be an independent predictor of malignancy." (PMID 36232418, 2022). "In a recently published study, rutin was found to cause apoptosis of cervical cancer cells by downregulation of the Notch-1 and Hes-1 genes." (PMID 36295828, 2022). "This can be explained by the fact that Notch-1 activation is associated with the onset and development of cervical cancer." (PMID 34683855, 2021). "In contrast, the association between cytoplasmic NUMB expression and cervical cancer was lost after adjusting for nuclear NOTCH1 expression (β = 2.074, 95% [CI] = –0.358, 4.506, P = 0.094)." (PMID 29721172, 2018). "We previously reported that Notch1 promotes cIAP2 transcription by NF-κB, and associates with IKKα at NF-κB-dependent promoters in cervical cancer cell lines." (PMID 30564555, 2018). "Previously, we reported that Notch1 associated with IKKα and regulated NF-κB activity in cervical cancer cells." (PMID 30564555, 2018). "To determine the potential effect of NOTCH1 on cervical cancer prognosis, we explored the association of NOTCH1 expression with overall survival (OS) in patients with malignant lesions." (PMID 29721172, 2018). "In cervical cancer, upregulation of Notch1 and Notch2 was associated with in-situ or invasive squamous cell carcinoma and adenocarcinoma, and it is thought that abnormal Notch signaling can promote the development of cervical cancer." (PMID 25381598, 2014). "In cervical cancer cells, Notch homolog 1, translocation-associated (Drosophila) (Notch1) and RhoC make similar phenotypic contributions to EMT, and Notch1 inhibition can reduce RhoC activity, suggesting that the latter plays a role as an effector of the former." (PMID 34627249, 2021). "Hes-1 and Notch-1 overexpression has been associated with the progression of cervical cancer." (PMID 34440505, 2021). "Taken together, our research indicated that ST3Gal IV was negatively associated with the pathological grade of cervical cancer tissues, and the overexpression of ST3Gal IV inhibited the growth and proliferation of cervical cancer cells in vivo and in vitro through Notch1/p21/CDKs signaling pathway." (PMID 33598419, 2020). "Activated expression of Notch-1 protein may be associated with carcinogenesis of normal cervical epithelium and may affect the development of cervical cancer." (PMID 31417656, 2019). "Cervical carcinoma, the second most prevalent cancer in women, is initiated and sustained in part by the presence of high-risk human papillomavirus oncogene expression (zur Hausen, 2002), and has an aberrant expression of Notch1, its ligand Jagged1 and downstream target Hes1." (PMID 19953094, 2010). "In vitro experiments using Caski cervical cancer cells have shown that rutin inhibits proliferation and induces apoptosis in a dose-dependent manner, accompanied by downregulated Notch1 and Hes1 expression." (PMID 41602823, 2026). "By screening the marker genes of plasma cells for ssGSEA, the results indicated that in the TCGA cervical cancer cohort, the plasma cell ssGSEA score was significantly negatively correlated with NOTCH1 expression (R=-0.310; p<0.05)." (PMID 41306984, 2025). "As the core molecule of this signaling pathway, NOTCH1 was significantly highly expressed in cervical cancer tissues and promoted cervical cancer cell proliferation in vitro." (PMID 41306984, 2025). "In terms of cell cycle regulation, in vitro experiments showed that cervical cancer cells with NOTCH1 knockdown exhibited significantly reduced proliferative capacity." (PMID 41306984, 2025).
cervical carcinoma (continued). "This study explored the role of NOTCH1 in cervical cancer from multi-omics perspectives, including single-cell sequencing, cDNA microarrays, high-throughput sequencing, and immunohistochemistry, combined with a series of in vitro and in vivo experiments." (PMID 41306984, 2025). "This indicates that has-miR-449a can inhibit the proliferation of cervical cancer cells via inhibited NOTCH1 expression in vitro (all p<0.05)." (PMID 41306984, 2025). "Through inducing apoptosis, causing G0/G1 phase arrest, and downregulating the levels of Notch-1 and Hes-1 in the Notch signaling pathway, these findings collectively demonstrate that rutin has strong anticancer effects in human cervical carcinoma Caski cells." (PMID 41142938, 2025). "By causing apoptosis, G0/G1 phase arrest, and downregulating the levels of Notch-1 and Hes-1 of the Notch signaling pathway, rutin demonstrated strong anticancer effects in human cervical carcinoma Caski cells." (PMID 41142938, 2025). "The NOTCH signaling pathway is aberrantly activated in multiple tumors, and NOTCH1, its core transmembrane receptor, is highly expressed in cervical cancer." (PMID 41306984, 2025). "This study reveals the specific mechanisms by which NOTCH1 promotes cervical cancer progression from two dimensions: cell-autonomous regulation and tumor microenvironment remodeling." (PMID 41306984, 2025). "While this study provides evidence for the role of NOTCH1 in cervical cancer, it still has limitations." (PMID 41306984, 2025). "This indicates that NOTCH1 can promote the G1-to-S phase transition of cervical cancer cells, thereby promoting the proliferation of cervical cancer cells." (PMID 41306984, 2025). "In this study, NOTCH1 overexpression significantly increased the survival rate of cervical cancer cells after irradiation." (PMID 41306984, 2025). "The curcumin analog PBPD induces cuproptosis and endoplasmic reticulum stress in cervical cancer cells via the Notch1/RBP-J/NRF2/FDX1 pathway." (PMID 40276654, 2025). "Compared with HPV-negative C33a cells and primary keratinocytes, NOTCH1 is downregulated in HPV-positive cervical cancer cell lines (such as CaSki)." (PMID 37994984, 2023). "During the early stage of cervical cancer, Notch1 is a cancer-promoting factor, but in the advanced stage of cervical cancer, Notch1 is transformed into a cancer-inhibiting factor." (PMID 35846128, 2022). "It was reported that autophagy controlled the epithelial-to-mesenchymal transition and metastasis of cervical cancer through the regulation of the NOTCH1 intracellular domain." (PMID 36016559, 2022). "Rutin has recently been demonstrated to regulate Notch-1 and Hes-1 mRNA levels in cervical cancer cells." (PMID 36295828, 2022). "Results indicated that rutin treatment significantly downregulated the mRNA expression of Notch-1 and Hes-1 genes of Notch signal transduction in human cervical cancer Caski cells." (PMID 34440505, 2021). "In cervical cancer cell lines, NOTCH1 mRNA expression was increased 4-fold in SiHa cells when compared to C33A cells (gray bars), although this expression remained lower than that found in HFK1." (PMID 34944802, 2021). "In adherent cervical cancer cells FTS co-precipitated with Notch1/cleaved Notch1/Hes1, suggesting FTS molecular interaction with Notch molecules." (PMID 34765546, 2021). "Altogether, these results showed that rutin showed potent anticancer effects in human cervical cancer Caski cells by triggering apoptosis, G0/G1 phase arrest, and downregulating the level of Notch-1 and Hes-1 of the Notch signaling pathway." (PMID 34440505, 2021). "The tumor suppressor p21, one of the Notch1 target genes, was also increased in cervical cancer cells overexpressed by ST3Gal IV." (PMID 33598419, 2020).
cervical carcinoma (continued). "The expression of p16INK4a, Notch1, and hTERC genes has a positive correlation with the occurrence and development of cervical cancer." (PMID 31976596, 2020). "The p16INK4a and Notch1 are overexpressed in cervical lesions, especially obvious in cervical cancer and CIN‐III, while the p16INK4a gene performs more prominently." (PMID 31976596, 2020). "In conclusion, ST3Gal IV expression inhibits the growth and proliferation of cervical cancer cells in vitro and in vivo through the Notch1/p21/CDKs signaling pathway." (PMID 33598419, 2020). "The value of p16INK4a, Notch1, and hTERC genes as molecular biological indicators for the development of cervical cancer and its precancerous lesions was compared." (PMID 31976596, 2020). "Most of the current studies believe that the expression rates of p16INK4a, Notch1, and hTERC genes in cervical precancerous lesions and cervical cancer are significantly better than other markers." (PMID 31976596, 2020). "In this study, the expression of the Notch1 gene was expressed in cervical cancer, CIN‐III, CIN‐II, CIN‐I, uterine leiomyoma, and chronic cervicitis." (PMID 31976596, 2020). "This study examined the expression of p16INK4a, Notch1, and hTERC genes in cervical cancer and precancerous lesions." (PMID 31976596, 2020). "Taken together, these results confirm that ST3Gal IV overexpression inhibits the proliferation of cervical cancer cells via the Notch1/p21/CDKs signaling pathway." (PMID 33598419, 2020). "In this study, Mongolian cervical cancer patients was designed to detect gene expression of p16INK4a, Notch1, and hTERC in HPV16‐infected tissues including cervical cancer, CIN‐III, CIN‐II, CIN‐I, uterine leiomyoma, and chronic cervicitis." (PMID 31976596, 2020). "In cervical cancer, Notch1 has been proven to regulate RhoC leading to changes in migration and invasion." (PMID 31340863, 2019). "Receptor blocker DAPT has synergistic effect on curcumin-PDT in the treatment of cervical cancer, which is mainly related to the down-regulation of Notch-1 and NF- κB expression." (PMID 31417656, 2019). "RhoC also regulates EMT in cervical cancer, wherein the inhibition of Notch1 and RhoC resulted in the abolition of actin stress fiber formation and fibronectin expression, the two important changes associated with EMT." (PMID 31340863, 2019). "Our studies had shown that DAPT itself inhibited Notch-1 mRNA and protein expression in cervical cancer in vitro and in vivo." (PMID 31417656, 2019). "In human cervical cancer, several reports indicate intracellular localization of the Notch1 protein." (PMID 30038662, 2018). "Poor survival of patients with nuclear NOTCH1 and 3 expressions has already been described in non-small cell lung cancer and cervical carcinoma." (PMID 29721172, 2018). "We had previously shown that Notch1 regulates NF-κB-induced c-IAP2 expression in cervical cancer cells in an IKKα-dependent fashion." (PMID 30564555, 2018). "The miR-34a suppresses invasion of cervical carcinoma and choriocarcinoma cells by targeting Notch1 and Jagged1." (PMID 28073349, 2017). "MiR-34a suppresses invasion via repression of Notch1 and Jagged1 in cervical carcinoma and choriocarcinomacells." (PMID 28281638, 2017). "Coactivation of Notch 1 and NF-kB signaling pathways at the cellular level is seen can be found in the majority of human cervical cancers." (PMID 26701206, 2016). "In cervical carcinoma cells, both Notch1 and RhoC have similar phenotypic contribution to EMT, and Notch1 inhibition decreases RhoC activity, suggesting that RhoC functions as an effector of Notch1." (PMID 24986540, 2014).